IL15 (interleukin 15)
Diseases named in the same sentence as IL15 in open-access papers (continued):
Sharing a sentence is not in itself a finding about the gene and the disease.
melanoma (continued). "IL-15 concentrations of 1140 pg/mL (Colo-679), 70 pg/mL (MeWo), and 200 pg/mL (IPC298) were detected in the supernatants of delNS1-IL-15-infected melanoma cells." (PMID 22563505, 2012). "In the present study, we used this approach for an IL-15 expressing delNS1 vector and showed that this delNS1-IL-15 virus replicates and produces IL-15 in permissive human melanoma cells." (PMID 22563505, 2012). "Ex vivo expansion of tumor specific lymphocytes using IL-15 and IL-21 produced fewer Tregs and more cytolytic cells against melanoma cell lines." (PMID 24281094, 2010). "The high incidence of expression of TGF-β, IL-8, IL-6, VEGF, PDGF-AA, OPN, IGF-1 and IL-15 by human melanoma supports consideration of these factors in future planning of therapy." (PMID 24281094, 2010). "Of importance, Nr2f6-deficient mice are protected against MHC-I negative B16-F10 melanoma lung metastasis formation, especially with IL-15 complex treatment, indicating the potential of NR2F6 to affect NKp46-dependent NK cell-mediated tumor surveillance." (PMID 39920136, 2025). "Melanoma-derived TNF displays dual functionality, acting as both a cytokine and growth factor by transferring to nearby melanoma cells via paracrine or juxtacrine routes, thereby activating NF-κB–mediated survival pathways, akin to IL-15 and IL-10 receptor signaling." (PMID 40443670, 2025). "We have previously shown in a phase I trial in dogs that inhaled recombinant human (rh) IL-15 is associated with anti-tumor activity in dogs with metastatic OSA and melanoma, observing an objective response rate of 11% and a clinical benefit rate of 39% among 18 evaluable dogs." (PMID 41209004, 2025). "Additionally, IL-15 levels rose significantly up to 4 weeks post-CPMV treatment in melanoma patient." (PMID 40386779, 2025). "In addition, recombinant IL-15 (rIL-15) has been found to promote regression of melanoma, colorectal cancer, and lymphoma tumors and reduce metastasis in transplanted tumor mouse models." (PMID 39221244, 2024). "GT-00AxIL15 also synergized with approved ADCC-mediating αEGFR or αPD-L1 mAbs in vitro and induced significant anti-tumor activity in combination with αPD-L1 treatment in a melanoma model that is non- or minimally responsive to IL-15 or αPD-L1/PD-1 monotherapy." (PMID 38338686, 2024). "In a melanoma mouse model, IL-15 promoted tumor progression by stimulating CD215+ myeloid cells." (PMID 38928238, 2024). "Similarly, oral administration of an oncolytic virus carrying a vector expressing IL-15 produced similar results in lung cancer and melanoma mouse models." (PMID 38361928, 2024). "The production of cytokines such as interleukin-15 (IL-15), induced by the exposure of skin cells to UV rays, could also promote melanoma development." (PMID 37334356, 2023). "Here we found that K2-Fc, an antibody derivative that blocks the PD-1:PD-L1 axis and enables enhanced ADCC, could augment IL-15/IL-15Rα-mediated melanoma cell killing and could synergistically improve CD8+ T cell and NK cell activation." (PMID 37923822, 2023). "Furthermore, statistical analysis revealed a significant difference (p < 0.05) in the expression intensity of IL-15 in melanoma samples compared with nevi." (PMID 37334356, 2023). "Finally, by analyzing public datasets, we studied the correlation between IL-15 and IL-15Rα expressions and melanoma stage, NK and T-cell markers, and overall survival (OS)." (PMID 37334356, 2023). "Since it has been recently shown that the activation of ADAM17 by IL-15 limits human NK cell proliferation, we propose that cleavage of the mbIL-15 by ADAM17 causes the spread of a soluble biological active complex within the melanoma TME." (PMID 37334356, 2023). "In stage I, II, and III melanoma samples, a higher level of expression and distribution of IL-15+ tumor cells were detected in the dermis and epidermis (p < 0.05) than in the nevi, whereas in metastatic samples virtually all tumor cells were strongly positive (p < 0.05 vs. nevi)." (PMID 37334356, 2023).
melanoma (continued). "In conclusion, melanoma appears to display complex mechanisms of immune activation and regulation that have not been completely clarified, and in which, for instance, the possible role of IL-15/IL-15Rα complex and isoforms has been underestimated." (PMID 37334356, 2023). "Moreover, the growth kinetics of a patient‐derived xenograft (PDX) melanoma were significantly delayed in HSC‐engrafted NSG‐Tg(Hu‐IL15) mice as compared to HSC‐engrafted NSG mice demonstrating that human NK cells have a key role in limiting the tumor growth." (PMID 35959876, 2022). "Moreover, HSC‐engrafted NSG‐Tg(Hu‐IL15) mice show enhanced inhibition of a patient‐derived xenograft (PDX) melanoma tumor growth in an NK cell‐specific manner." (PMID 35959876, 2022). "In clinical trials using an ex vivo monocyte-derived DC vaccine to prevent melanoma, GM-CSF and IL-15 treatment preferentially elicited LC-type DC, which are more efficient in priming melanoma-antigen-specific CD8+ T cells in vitro than their monocyte DC counterparts." (PMID 36146458, 2022). "Finally, we also showed therapeutic effects on B16F10-OVA melanoma by treatment with the MMC-treated IL-15:IL-15Rα-B16F10-OVA vaccine in mice." (PMID 34439192, 2021). "IL15 stimulation with TIGIT blockades reverses altered CD155-mediated NK cell function in melanoma." (PMID 33810032, 2021). "The delivery of plasmid IL-15 by GET into tumor tissue led to the regression of B16 melanoma in mice, hence we investigated if this strategy could benefit breast cancer bearing animals." (PMID 33628206, 2020). "Moreover, in human melanoma, local IL‐15 levels strongly correlated with tumor‐resident CD8+ T‐cell numbers, and high IL‐15 levels were associated with a more favorable prognosis." (PMID 31230406, 2019). "Also, cells stimulated with IL-15 and IL-21 mediated enhanced immunity in mice with melanoma compared to T cells expanded in the presence of either IL-15 or IL-21 alone." (PMID 30842774, 2019). "Similarly, only P14 TCR transgenic T cells stimulated with the gp33-44 peptide with IL-15 mediate tumor immunity to B16gp33 melanoma cells." (PMID 28239463, 2017). "Besides the beneficial role of IL-15 in viral infections, application of an IL-15 fusion protein significantly reduced tumor growth and progression in a melanoma mouse model, which was correlated with enhanced NK cell activity." (PMID 28904191, 2017). "We then assessed the effect of IL-15 on the survival and antitumor activity of adoptively transferred tetramer+ T cells in a metastatic melanoma model, in which mice were injected i.v. with Mel 624 melanoma cells (2×105 per mouse)." (PMID 26824989, 2016). "In the present study, we observed that in vivo treatment with IL-15 dramatically promoted the survival and/or proliferation of activated MART-1-TCR+ CD8 T cells, which was associated with a significantly increased antitumor effect, in melanoma-bearing hosts." (PMID 26824989, 2016). "IL-15Rα also mediates the anti-tumor effect of IL-15 in a B16 melanoma mouse model." (PMID 26993600, 2016). "Assuming that ACT of TRP-1-specific CD4+ T cells could reject established melanoma tumors in IL-15−/−RAG−/− mice, we could use this model to dissect the activity of NK cells on adoptively transferred CD4+ T cells without also activating Fc receptors." (PMID 26405570, 2015). "In addition, infection of melanoma cells with delNS1-IL-15 resulted in the production of high levels of biologically active IL-15." (PMID 22563505, 2012). "Such activation releases IFN-I, chemokines CXCL10 and CCL5, and cytokines interleukin-15 (IL-15)/IL-15R and IL-18, thereby allowing crosstalk of NK cells and dendritic cells for reprogramming of macrophages for an improved therapeutic outcome in melanoma patients." (PMID 39802449, 2024).
melanoma (continued). "Since in melanoma patients’ high monomeric IL-15 serum levels have been reported to correlate with a poor clinical outcome, we asked what could be the consequences of a too-high and constant production of the IL-15/IL-15Rα complex." (PMID 37334356, 2023). "During initial experiments splenic NK cells were cultured for 6 days in low dose IL15, a cytokine required for Dendritic cell-mediated NK cell priming in vivo (called “cultured NK cells” hereafter), purified by magnetic bead cell sorting prior to being co-cultured with B16 melanoma cells for 18 h." (PMID 31595191, 2019). "Furthermore, using hu-mouse-derived melanoma antigen-specific human T cells, we demonstrate that pretreatment of the T cells with rapamycin can significantly enhance the antitumor activity of adoptive T cell therapy in IL-15-treatted recipients." (PMID 26824989, 2016). "However, IL-15 has also been shown to stimulate a melanoma cell line that expressed the IL-2R." (PMID 24281094, 2010). "Thus, treatment with IL-21 + low-dose IL-2 after the adoptive transfer of pmel Tg CD8+ T cells into mice with established B16 melanoma tumors (pmel Tg/B16 model) might yield anti-tumor effects comparable to or greater than those observed with IL-21+IL-15." (PMID 16772043, 2006). "Collectively, these data show that in melanoma, although γδ T cells appear capable of producing cytokines, induction of LAG-3 and CTLA-4 in response to TCR and IL-15 is impaired." (PMID 41310392, 2026). "al. developed in situ–forming thermosensitive hydrogels synthesized from poly(ethylene glycol)-poly(γ-ethyl-L-glutamate) diblock copolymers (mPEG-b-PELG) for the co-delivery of interleukin-15 (IL-15) and cisplatin (CDDP) against melanoma." (PMID 37587290, 2024). "Indeed, in pre-clinical melanoma models, the presence in melanoma cells and/or stromal cells of the IL-15/IL-15Rα complex (either in membrane-bound or soluble form), or treatment with IL-15clpx, may lead to the inhibition of tumor progression and reduction of the lung and liver metastases." (PMID 37334356, 2023). "In the first in-human study, metastatic patients with melanoma and renal cell carcinoma (RCC) treated with intravenous (i.v.)recombinant human IL-15 (rh-IL15) displayed an expansion of NK cells, plus memory and γδ T cells." (PMID 37371081, 2023). "The immunohistochemical images of IFNGR2, CCL25, IL15, RTP4, and NLRP6 in both normal skin tissue and melanoma tissue confirmed the expression of the GRIPs in CM." (PMID 35492358, 2022). "With the improved development and function of human NK cells in HSC‐engrafted NSG‐Tg(Hu‐IL15) mice, we next evaluated the growth kinetics for a PDX melanoma in these mice." (PMID 35959876, 2022). "Another fourth generation CAR targeting VEGFR2 on the tumor vasculature and co-expressing murine IL-15 has been evaluated as a tool to overcome TME immunosuppression in immunocompetent, syngeneic melanoma-bearing mice." (PMID 35211124, 2022). "HSC‐engrafted NSG‐Tg(Hu‐IL15) and NSG mice were implanted subcutaneously with 2.5 million PDX melanoma cells." (PMID 35959876, 2022). "In mice bearing subcutaneous B16F10 melanoma and CT26 colon carcinoma, tissue biodistribution analysis demonstrated significantly greater retention of N-803 in lymphoid organs compared to IL-15." (PMID 35806311, 2022). "Upon DNA transfection of murine B16.F1 melanoma and CT26.CL25 colorectal carcinoma cells, we assessed the activity of secreted IL15 by incubating the CTLL‐2 murine cytotoxic T lymphocytes with media from transfected B16.F1 and CT26.CL25 cells." (PMID 35758207, 2022). "In B16F10 melanoma mouse models, RLI displayed a longer in vivo half-life and higher efficiency than IL-15 or IL-2 in reducing lung and liver metastasis and prolonging survival." (PMID 35806311, 2022).
melanoma (continued). "Here, we demonstrated that IL12, IL15, and IL18 receptor induced ML NK cells from HD and patients with advanced melanoma exhibit an enhanced ability to attack melanoma targets." (PMID 34187852, 2021). "ML NK cells from HD were generated following IL12, IL15, and IL18 receptor activation using PBMC allowed to differentiate, and then restimulated with the human melanoma cell lines DM6 and M14." (PMID 34187852, 2021). "This study reports the use of the BacMam system to deliver and express self-assembling IL-15 and IL-15Rα genes to murine B16F10 melanoma and CT26 colon cancer cells." (PMID 34439192, 2021). "Combined administration of IL15 and IL21 had synergistically accelerated the growth of both naive and memory CD8 T cells and resulted in tumor regression in a murine model of melanoma." (PMID 33381115, 2020). "Promising results have been obtained in phase I clinical trials for melanoma and hematologic malignancies using ALT-803 (an IL-15 mutein/IL-15Rα complex fused with the IgG1 Fc)." (PMID 33584718, 2020). "In vitro expansion is also similar when either high dose IL-2 (1000 IU/ml), IL-15, or a combination of the two is used for human CD8 αβ T cells specific for melanoma, influenza, Epstein-Barr virus, and cytomegalovirus." (PMID 28239463, 2017). "NK cells, cultured with IL-2, IL-15 or IL-15/IL-18 and in the presence of either BRAF-i or MEK-i, were analyzed for their ability to kill different melanoma cell lines including MeCoP, MeTA, MeDeBO and FO-1." (PMID 27563819, 2016). "For example, IL-15 can also induce the expansion of NK and CD8+ T cell populations and thereby suppress the growth of malignant melanoma, and a complex of IL-15 and soluble IL-15Rα has even more potent effects." (PMID 26772545, 2016). "Moreover, NK cells from melanoma metastatic lymph nodes were found surrounding tumor cell clusters and although they were mostly CD56bright and inactive, they could be activated ex vivo by IL-2 or IL-15 and could lyse metastatic melanoma cells more efficiently than blood-derived NK cells." (PMID 25674087, 2015). "Based on the success of IL-15 in animal models, the first clinical trials have begun (NCT01727076, NCT01021059, NCT01572593) in multiple tumor types including melanoma, renal cell carcinoma and non-small cell lung carcinoma patients." (PMID 25879689, 2015). "The combination of IL-21 and IL-15 was also administered IP subsequent to human gp10025–33 (hgp10025–33) peptide vaccination of lymphopenic, tumor-bearing (B16F10 melanoma) C57BL/6 mice." (PMID 16772043, 2006). "A recent phase 1 trial demonstrated that inhaled recombinant human interleukin-15 (rhIL-15) immunotherapy is safe and may be effective against lung metastases in dogs with metastatic OSA or melanoma." (PMID 41041167, 2025). "For example, a fusion complex combining an IL-15 agonist coupled with a TGF-β molecular sink showed increased infiltration of both NK and CD8+ cytotoxic cells and lower tumor burden in a syngeneic mouse B16F10 melanoma model." (PMID 37205105, 2023). "To extend this to an in vivo model of adoptive transfer immunotherapy, we next expanded purified TCR-transgenic GP100-reactive CD8+ T cells in IL-2, IL-15, or OMCPmutIL-2 for 2 weeks and adoptively transferred them to C57BL/6 mice bearing established B16 melanoma." (PMID 35603788, 2022). "Depletion of CD8+ T cells in the PDX melanoma bearing NSG‐Tg(Hu‐IL15) mice did not significantly change the tumor growth rates as compared to isotype control treated HSC‐engrafted NSG‐Tg(Hu‐IL15) mice." (PMID 35959876, 2022).
melanoma (continued). "DCs matured in vitro in the presence of melanoma EVs demonstrated significantly impaired expression of CD83 and CD86 as well as decreased expression of Th1 polarizing chemokines Flt3L and IL15 and migration chemokines MIP-1α and MIP-1β compared to liposome-treated DCs." (PMID 28424693, 2017). "In the Pmel-1 murine melanoma model, the majority of Pmel-1 CD8 αβ T cells expressing transgenic TCRs specific for the self/tumor specific peptide, gp10025–33 are naive when stimulated in vitro with the gp10025–33 peptide and either IL-2 or IL-15." (PMID 28239463, 2017). "In vitro expanded tetramer+ CD8+ T cells were cultured with rapamycin (100nM) for 3 days immediately before transfer into IL-15-treated or non-treated melanoma-bearing recipients that were injected i.v. with Mel 624 melanoma cells (1×105 per mouse)." (PMID 26824989, 2016). "ACT of TRP-1-specific CD4+ T cells was able to reject established B16.F10 melanoma tumors and increase survival in IL-15−/−RAG−/− hosts relative to RAG−/− hosts without the addition of antibodies." (PMID 26405570, 2015). "We observed in transplantable melanoma, glioma and metastatic breast carcinoma models that DCIL-15-based DNA vaccines in which DC specifically express IL-15 and simultaneously produce tumor Aghsp70 were able to mediate potent therapeutic efficacy that required both host Batf3+ DC and CD8+ T cells." (PMID 25941586, 2014). "This was confirmed in our experimental setting: IL15-only expressing virus, consistent with published data, showed therapeutic effect against murine melanoma tumors in the RAG1-knockout background indistinguishable from vMyx-tdTr." (PMID 25329832, 2014). "The nuclear localization of IL-15, similar to that reported in MELREO melanoma cells, is probably mediated by its specific receptor IL-15Rα, as IL-15 does not appear to be able to enter the nucleus by itself." (PMID 23950892, 2013). "In oncolysis sensitive melanoma cells, delNS1-IL-15 (but not delNS1) infection resulted in the production of IL-15 levels ranging from 70 to 1140 pg/mL in the cell culture supernatants." (PMID 22563505, 2012). "Since IL-15 is produced by a vast diversity of cells in vivo, we can postulate that endogenous IL-15 is presented by IL-15Rα harbored by Dex leading to significant NK cell proliferation in vivo after Dex vaccination and NKG2D restoration in melanoma patients." (PMID 19319200, 2009). "The study recruited dogs with histopathological diagnoses of oral malignant melanoma, generated their peripheral blood mononuclear cells, expanded them into predominantly non-B non-T cells via stimulations of IL-15, IL-2, and IL-21, and then re-infused the cells into tumor-bearing dogs." (PMID 38668417, 2024). "For instance, preclinical studies using subcutaneous B16 or B16F-10 melanoma models describe the induction of TLS following therapies aimed to improve DC function, including artificial adjuvant vector cells (aAVCs), STING adjuvants and oncolytic adenoviruses carrying IL-15 (Ad-IL15)." (PMID 37954592, 2023). "Curiously, in in vitro studies, IL-15 combined with TIGIT inhibition has also been found to increase the activity of NK cells’ cytotoxicity versus that of melanoma cells, and to reduce the development of tumor metastasis in mouse melanoma and soft tissue sarcoma models." (PMID 36231109, 2022). "However, it was later shown that exosomes derived from NK-92 MI cells had antitumor effects on melanoma both in vitro (B16F10 cells) and in vivo, and those isolated from IL-2/IL-15–activated NK cells showed cytotoxicity in breast cancer cell lines (MDA-MB-231/F and MCF-7)." (PMID 34093547, 2021). "Notably, IL-15 can increase the expression of both CD226 and TIGIT by intra-tumoral NK cells, and combination therapy of IL-15 and TIGIT blockade increased cytotoxicity of NK cells against melanoma and suppressed lung metastasis in mouse melanoma models." (PMID 34367161, 2021).